TREM2 (triggering receptor expressed on myeloid cells 2)
Diseases named in the same sentence as TREM2 in open-access papers (continued):
Sharing a sentence is not in itself a finding about the gene and the disease.
dementia (continued). "However, TREM2 was not thought to be a potential candidate gene for dementia until TREM2 mutations were discovered in a Lebanese family with early-onset dementia but no PLOSL." (PMID 38396996, 2024). "For instance, the TREM2 gene, coding for a microglial lipid sensor that interacts with several factors involved in the metabolism of lipids, could decrease the occurrence threshold of dementia." (PMID 32908482, 2020). "Furthermore, recent epidemiological studies have demonstrated that serum levels of a soluble form of triggering receptor expressed on myeloid cells 2 (TREM2) may have clinical significance as a potential novel predictive biomarker for dementia incidence." (PMID 32183348, 2020). "Recently, soluble fragments of the triggering receptor expressed on myeloid cells 2 (sTREM2) protein in CSF have been reported to be increased in prodromal AD and also in individuals with TREM2 rare genetic variants that increase the likelihood of developing dementia." (PMID 31779670, 2019). "The extended haplotype of DS participants who carried the TREM2 R47H mutation was impressive: D7 (male, 37 years old, ApoEɛ3/ɛ3, Tau H2/H2, TREM2C/T, and HLA-DR A/G) was non-demented, whereas D4 was (female, 39 years old, carrying ApoEɛ3/ɛ4, TauH1/H2, TREM2-C/T, and HLA-DR A/A) developed dementia." (PMID 30909239, 2019). "Cerebrospinal fluid sTREM2 levels were found to be significantly reduced in patients with dementia harboring NHD-associated TREM2 variants, and reduced shedding of sTREM2 was observed in human kidney cell lines overexpressing NHD-associated mutant forms of TREM2." (PMID 30157425, 2018). "When these data is combined with data we have previously published we conclude that among 105 dementia patients, 5.7% are attributable to PSEN1 mutations (6/105), 2.9% (3/105) to C9ORF72 and TREM2 each, and 0.95% (1/105) to MAPT, GRN and NOTCH3 each, while 85.7% (90/105) remain unclear." (PMID 27632209, 2016). "Nasu–Hakola disease, a systemic bone cystic disorder with progressive presenile dementia followed by extensive sclerosis in the front-temporal lobe and the basal ganglia, occurs due to genetic mutation of TREM-2 and DAP12 resulting in aberrant TREM-2/DAP12 signaling pathway." (PMID 24395130, 2014). "Current evidence therefore suggests that TREM2 levels in CSF or peripheral blood, although not sensitive enough to serve as a diagnostic biomarker, can predict the risk of early cognitive involvement and dementia in PD patients, and even the risk of motor progression." (PMID 40309835, 2025). "Early evidence implicating the role of TREM2 in neuropathology was provided from a study on Nasu–Hakola disease (NHD), a rare disorder characterized by progressive, early‐onset dementia." (PMID 41476737, 2025). "In dementia and MCI, microglia in the central nervous system are activated and expression of TREM2 increases, with release of sTREM2 into the CSF." (PMID 35615588, 2022). "It is possible that the lack of statistical interaction between sTNFR2 and sTREM2 levels on AD biomarkers among A+T+ CN, MCI and dementia suggests altered TNFR2 and TREM2 pathway activations in AD." (PMID 34276339, 2021). "However, it is not known how these Trem2 species, predisposes individuals to presenile dementia." (PMID 33115519, 2020). "Therefore, it was hypothesized that TREM2 may be a risk allele associated with other forms of dementia that have not previously been screened for TREM2 mutations because of their atypical (non-NHD/PLOSL) clinical presentation." (PMID 26337043, 2015). "iPSCs derived from lymphoblasts from two LOAD patients carrying the TREM2 R47H risk variant (AD2-2 and AD2-4), as well as aged-matched control individuals without dementia (CON8 and CON9) were used for this study." (PMID 32630447, 2020). "Beyond this, reduced average PC3 loading in LBD suggests this cohort may harbour TREM2 dynamics that are dissimilar to other dementias as these cells comprise the negative end of PC3 (opposite to PC1 composition)." (PMID 39472664, 2025).
dementia (continued). "Soluble triggering receptor expressed on myeloid cells 2 (TREM2), a receptor found on microglia, is also found at higher levels in the CSF of patients with delirium in the absence of pre-existing dementia, which highlights the importance of stratifying delirium patients by their dementia status." (PMID 39463449, 2025). "AS dysregulation in genes like MAPT (tau isoforms), TREM2 (microglial function), and RNA-binding proteins (TDP-43, FUS) underpins dementia but has never been systematically studied in AfrAbian cohorts." (PMID 40600167, 2025). "Wild-type TREM2 carriers D11 (female, 48 years old was carrying ApoEɛ2/ɛ3, Tau H2/H2, TREM2C/C, and HLA-DR G/G) and D12 (male, 46 years old was carrying ApoEɛ3/ɛ3 Tau H2/H2, TREM2C/C, and HLA-DRA/G) had not developed dementia, indicating that H2 homozygosity could be protective in DS subjects." (PMID 30909239, 2019).
Cognitive impairment (79 papers, 2016 to 2026). Abnormal cognition is characterized by deficits in thinking, reasoning, or remembering. "In this study, we knocked out TREM2 in the mutant A53T α-Syn transgenic mice (A53T mice) to investigate the effect of TREM2 deficiency on cognitive impairment in PD mice, as well as synaptic plasticity and the degradation of α-Syn in their hippocampus." (PMID 40393958, 2025). "To investigate the effect of TREM2 deficiency on cognitive impairment while avoiding confounding effects from motor deficits, we conducted experiments when the mice were 12 months old." (PMID 40393958, 2025). "In conclusion, TREM2 deficiency aggravates cognitive impairment by exacerbating α-Syn-induced microglial lysosomal dysfunction via the ERK1/2 signaling pathway." (PMID 40393958, 2025). "Conversely, reduced TREM2 levels were associated with neurofibrillary tangle degeneration, cognitive impairment, and activation of inflammatory responses." (PMID 40806186, 2025). "In conclusion, TREM2 deficiency exacerbates cognitive impairment in PD by exacerbating α-Syn-induced microglial lysosomal dysfunction, identifying TREM2 as a potential therapeutic target." (PMID 40393958, 2025). "Carrying p.R47H in the TREM2 gene was associated with mild cognitive impairment, amyloid deposition, and microglial activation in a study on influenza vaccine immune challenge." (PMID 40362170, 2025). "Loss of TREM2 impairs neuronal synapses in mice, exacerbates cognitive impairments and reduces the microglial barrier around plaques in correlation with the decreased plaque clearance rate in AD mice." (PMID 38464534, 2024). "Overexpression of TREM2 reduces activated microglia, Aβ deposition, synaptic and neuronal loss, neuroinflammation, and attenuates cognitive impairment." (PMID 38956653, 2024). "This is likely also mediated by TREM2, as knocking out TREM2 in mice resulted in an amplified spread of tau and correlated with synaptic loss and cognitive impairment." (PMID 37238932, 2023). "HIV (human immunodeficiency virus) associated cognitive disorder is also associated with the expression and functional role of TREM2." (PMID 37335084, 2023). "We found that eight AD and two patients with mild cognitive impairment (MCI) were carriers of the TREM2 R62H allele (rs143332484), which gives an allele frequency of 4.9%." (PMID 35120450, 2022). "Peripheral TREM2 mRNA levels are increased in AD and are related to AD-associated cognitive impairment and hippocampal atrophy, and the presence of the APOE ε4 allele further increases peripheral TREM2 expression." (PMID 35658903, 2022). "Recent studies have found that using adeno-associated virus or lentiviral particles to overexpress Trem2 alleviates Aβ deposition and cognitive deficits in APP/PS1 mice." (PMID 35658903, 2022). "Under oxidative stress, cleavage of TREM2 caused by neuroinflammation creates sTREM2 and stops the TREM2 signaling cascade, leading to cognitive impairment." (PMID 35615588, 2022). "In our previous study, we found that the expression of serum soluble TREM2 was decreased and serum soluble TREM2 levels were an independent risk factor for cognitive impairment in VD patients." (PMID 32617097, 2020). "Further investigation revealed that TREM2 overexpression attenuates cognitive deficits and neuronal loss." (PMID 32617097, 2020). "Taken together, in our current study, we provide novel evidence that TREM2 overexpression attenuates cognitive deficits and neural loss through modulating the phenotype of activated microglia and reducing inflammatory reaction." (PMID 32617097, 2020). "Additionally, elevated TREM2 and ApoEε4 expression showed region-specific associations—correlating with cognitive deficits in the CA1 and social deficits in the DG." (PMID 40859005, 2025). "There revealed that TREM2 deficiency could amplify or accelerate the α-Syn-induced damage of hippocampal neurons, leading to aggravated cognitive impairment in PD mice." (PMID 40393958, 2025).
Cognitive impairment (continued). "Notably, TREM2 deficiency aggravates hippocampal neurodegeneration and synaptic plasticity impairment in the A53T mice, resulting in more severe cognitive impairment." (PMID 40393958, 2025). "It remains to be investigated whether ATP11B exerts its therapeutic effects on pathological LDs primarily through signaling pathways associated with ApoE4 and TREM2, ultimately improving cognitive impairment and AD pathology in AD mice." (PMID 40123832, 2025). "TREM2 mutations promote aberrant activation of microglia in the brains of AD mice, reducing microglial reactivity to amyloid plaques, and leading to synaptic injury and cognitive impairment." (PMID 38956653, 2024). "In addition, results from AD mouse models suggested that TREM2 deficiency increased the volume of neuritic plaques in brain, induced tau hyperphosphorylation, promoted neuroinflammation, and exacerbated cognitive impairment." (PMID 37697966, 2024). "Loss of TREM2 function can lead to impaired synaptic maintenance in critical brain regions such as the cortex and hippocampus, potentially resulting in neuronal dysfunction and cognitive impairment." (PMID 38203185, 2023). "TREM2 functions are essential for phosphorylated Abeta sensing and its subsequent clearance by microglial cells in the brain, and a compromise in these functions has been associated with cognitive impairments." (PMID 36145091, 2022). "The potential role of TREM2 variants as a factor linked to cognitive progression of HD supports the hypothesis that inflammation might also contribute to the cognitive impairments seen in this disorder." (PMID 31724242, 2020). "We recently reported that overexpression of TREM2 in the hippocampus alleviates DIO-induced cognitive dysfunction and modulates microglial polarization to an anti-inflammatory state in mice, suggesting that TREM2 might be a novel target of DIO-associated cognitive impairment." (PMID 38464534, 2024). "Moreover, TREM2 may regulate the release of inflammatory factors by modifying the microglia phenotype, which may partly explain the protective effects of TREM2 against cognitive deficits and neuronal loss in the mouse models of VD." (PMID 32617097, 2020). "Furthermore, in late-onset AD cases, higher CSF PGRN levels were associated with more advanced disease stages and cognitive impairment, and once pathology had commenced correlated with CSF levels of soluble triggering receptor expressed on myeloid cells 2 (TREM2)." (PMID 30862089, 2019). "Although research on TREM2 has revealed how microglia are regulated, some obvious challenges still exist when applying these findings to understand cognitive impairment after SCI." (PMID 41280332, 2025). "Here, we propose that the empirical knowledge in AD can provide important clues for exploring the role of the TREM2 signaling pathway-mediated microglial cell response in cognitive impairment following SCI." (PMID 41280332, 2025). "Taken all together, these observations place TREM2 as both a key regulator of microglial activity and as a potential drug target to prevent cognitive impairment in AD." (PMID 41280332, 2025). "TREM2 improves neuroinflammatory reactions and cognitive impairment in AD mice through PI3K/AKT/FoxO3a signaling pathway." (PMID 40676546, 2025). "HLJD decoction can effectively alleviate cognitive impairment by inhibiting the Trem2/Dap12 signaling pathway related microglial neuroinflammation." (PMID 40234956, 2025). "The Chinese herb pyrolae herba demonstrates dual benefits: it suppresses hippocampal inflammation and improves cognitive deficits in LPS-treated mice through regulation of the TREM2 pathway." (PMID 41168805, 2025). "Preclinical studies have demonstrated that TREM2 agonists enhance microglial clearance of pathological proteins and promote metabolic resilience, reducing amyloid burden and cognitive deficits." (PMID 40940798, 2025).
Cognitive impairment (continued). "This provides a solid basis for the protective role of TREM2 in PD, suggesting a possible research direction for early intervention and treatment of cognitive impairment in PD." (PMID 40393958, 2025). "Multiple studies in humans have demonstrated significantly elevated levels of TREM2 in the plasma of patients with AD and mild cognitive impairment (MCI) compared to cognitively unimpaired controls." (PMID 41168805, 2025). "Taurine similarly ameliorates aberrant microglial reactivity and cognitive deficits, partly via upregulating TREM2." (PMID 41373648, 2025). "Alpinae Oxyphyllae Fructus (AOF) has been proven to regulate TREM2 and mitigate LPS-induced neuroinflammation, promoting a beneficial M2 phenotype in microglial cells and ameliorating cognitive impairments in mice." (PMID 38627829, 2024). "In a recent study, it has been shown that TREM2 has emerged as a promising therapeutic target for AD treatment since TREM2 overexpression rescued cognitive impairments in mice models by inhibiting microglia‐mediated neuroinflammation." (PMID 38888203, 2024). "The microglia receptor TREM2 has been shown to mitigate central inflammation and cognitive impairment in AD mice by decreasing M1-like microglia and regulating the PI3K/AKT/FoxO3a signaling pathway." (PMID 38464534, 2024). "The activated PI3K/Akt signaling pathway induced by TREM2 mediates the shift of microglia from the M1 to the M2 phenotype in response to CNS inflammation, thereby improving cognitive impairment." (PMID 39758888, 2024). "For the clinical and neuropsychological assessments, TREM2 p.R47H carriers were compared to a mild cognitive impairment and a healthy control group (clinical controls)." (PMID 37990275, 2023). "Compared to participants with mild cognitive impairment, TREM2 carriers had lower TSPO signal in Braak II (P = 0.04) and Braak III (P = 0.046) regions, despite having a similar burden of tau and amyloid." (PMID 37990275, 2023). "In a study conducted on brain tissues of 52 HIV-positive patients diagnosed with relative cognitive disorders had altered expression of TREM2 and TNFα." (PMID 37335084, 2023). "One TREM2 p.R47H carrier and two mild cognitive impairment participants reached the threshold for abnormal amyloid pathology." (PMID 37990275, 2023). "TREM2 p.R47H carriers were slightly younger than the mild cognitive impairment group (64.9 vs 71.6; P = 0.02) and clinical control group (64.9 vs 73.1; P = 0.005)." (PMID 37990275, 2023). "We compared baseline differences in microglial activation between TREM2 p.R47H carriers and both participants with mild cognitive impairment and an imaging healthy control group." (PMID 37990275, 2023). "TREM2 is also a potential target for the treatment of AD, and is this mechanism present in postoperative cognitive defects?" (PMID 38680509, 2023). "Conversely, the hippocampal overexpression of TREM2 attenuated microglial activation and cognitive impairment in mice fed with HFD for 50 weeks." (PMID 35884685, 2022). "For instance, TREM2 alleviates neuroinflammation and cognitive impairment through PI3K/AKT/FoxO3a signaling in AD mice; conversely, this neuroprotective effect of TREM2 can be eliminated with PI3K inhibitors." (PMID 35096262, 2022). "Using the same strategy, selective TREM2 overexpression on microglia was shown to ameliorate neuropathologies and spatial cognitive impairments in the tau transgenic mice, which suggests the protective role of TREM2 in tau pathology." (PMID 36389767, 2022). "We developed a mAb engaging the ECD domain of TREM2 that has been shown to attenuate cognitive impairment in amyloidopathy models." (PMID 33422057, 2021). "TREM2 activation was lower in AD microglia than in microglia from healthy subjects or patients with mild cognitive impairment." (PMID 34523252, 2021).